LCN2 (lipocalin 2)
Diseases named in the same sentence as LCN2 in open-access papers (continued):
Sharing a sentence is not in itself a finding about the gene and the disease.
Obesity (continued). "Several studies, in pre-clinical models and in humans, have revealed LCN-2 as biomarker in obesity, insulin resistance and hyperglycemia." (PMID 38396890, 2024). "Lipocalin-2 (LCN-2), a glycoprotein secreted by osteoblasts and adipocytes, functions as a pro-inflammatory factor in obesity-related metabolic disorders, despite our limited understanding of the potential LCN-2 receptors." (PMID 38532900, 2024). "The regulation of the insulin pathway by RBP4 or AGP, the involvement of A1M in obesity, endoplasmic reticulum stress, and the role of LCN2 and AGP in modulating food intake behavior are only some of the noteworthy features." (PMID 38673873, 2024). "Because LCN2, an adipocytokine, is closely related to adipocyte death and inflammation in obesity, we evaluated the effects of IF on LCN2 protein levels in HFD mice." (PMID 38201988, 2024). "Second, serum LCN2 levels were upregulated in four different mouse models of obesity (Leprob/ob, Leprdb/db, Mc4r−/−, and HFD‐fed mice) as compared to wide‐type littermate controls." (PMID 38035773, 2024). "We initially Sanger-sequenced the LCN2 gene in 287 female patients with AN and 284 children, adolescents with severe obesity." (PMID 37025415, 2023). "Although, it has been found that a 12-week HIIT period lowered circulating lipocalin-2 levels together with decreased body fat values in young men with obesity, such findings among adolescent boys with obesity are still lacking." (PMID 37238398, 2023). "Sanger sequencing of the coding region of LCN2 in 284 children and adolescents with severe obesity or 287 patients with anorexia nervosa." (PMID 37025415, 2023). "It has been suggested that LCN2 is a potential mediator linking chronic low-grade inflammation with obesity." (PMID 38203346, 2023). "In this scenario, obesity take part to EAE disease progression by releasing higher amount of LCN2 from adipose depots." (PMID 37517520, 2023). "Circulating LCN2 is positively correlated with adiposity, triglyceridemia, insulin resistance, and obesity-related metabolic disorders, as well as heart failure and renal syndrome." (PMID 37778719, 2023). "Contrarily, however, numerous studies indicated the anti-diabetogenic and anti-obesity properties of LCN2." (PMID 38203346, 2023). "Plasma LCN2 is known as a biomarker of acute kidney injury, arthritis, acute pancreatitis, obesity, cardiovascular disease, and multiple sclerosis." (PMID 37408474, 2023). "Increased levels of LCN2 were noticed in metabolic disturbances such as obesity, T2DM, hypertriglyceridemia, hyperglycaemia, PCOS and preeclampsia." (PMID 38203346, 2023). "Inflammatory features occurring in diabetes and obesity correlated with elevated LCN2 levels in blood plasma and some tissues in both humans and laboratory animals suggest a pro-diabetogenic and pro-obesity function of LCN2." (PMID 38203346, 2023). "Lipocalin-2 is upregulated in adipose tissues and the liver in obesity, and as lipocalin-2 decreases food intake and promotes fat cell browning, this indicates higher lipocalin-2 levels to counteract obesity and metabolic diseases." (PMID 37189804, 2023). "In mice, the disruption of Lcn2 resulted in insulin resistance, which significantly potentiated diet-induced obesity and fatty liver disease." (PMID 37638032, 2023). "Despite the well-studied role of lipocalin-2 in the immune response to bacterial infections, there is also evidence of its role as a pro-inflammatory adipokine in obesity and related metabolic diseases." (PMID 37240282, 2023). "In humans, lcn2 is highly expressed among others in the liver and adipose tissue, and circulating LCN2 has been identified as an inflammatory marker closely related to obesity and its metabolic complications." (PMID 36998471, 2023). "Unlike leptin, preclinical models support a more significant role for the adipokine lipocalin-2 (Lcn2) in obesity-driven PDAC." (PMID 37648285, 2023).
Obesity (continued). "Among severe obesity patients, serum LCN2 levels were significantly increased (111.59 ± 51.16 ng/mL vs. 92.68 ± 32.68 ng/mL, P = 0.035)." (PMID 35034646, 2022). "Recently, myriad of studies have devoted considerable attention to lipocalin-2 (LCN2) for its potential as a novel therapeutic target for obesity." (PMID 35138515, 2022). "An in vivo study using the PDAC mice model with diet-induced obesity found that adipokine lipocalin-2(LCN2) expression in PDAC tissue was upregulated." (PMID 35740306, 2022). "Adipocytes abundantly express LCN2, the expression of which is promoted during adipogenesis in a C/EBP-dependent manner and is thought to drive obesity-associated insulin resistance." (PMID 35406450, 2022). "Many studies have reported that LCN2 functions as proinflammatory adipocytokine involved in obesity-related metabolic complications and inflammatory diseases." (PMID 35884685, 2022). "For patients with severe obesity, serum LCN2 levels were much higher, suggesting that LCN2 levels were elevated in individuals with higher BMI and more severe hepatic steatosis." (PMID 35034646, 2022). "Although further investigation is needed in both experimental and clinical studies, lipocalin 2 is expected to be a new therapeutic target to control appetite and obesity." (PMID 35216490, 2022). "Pro-inflammatory TNF-α has been shown to induce LCN2; the adipokine LCN2 has been positively correlated with obesity and is reported to mediate insulin resistance in humans." (PMID 36329549, 2022). "Liver RNA-seq analyses revealed that several genes (including the obesity-promoting Lcn2 gene) that were upregulated by HFD in GABAAR WT mice, failed to be induced in Gabrg2F77I/F77I mice." (PMID 35436993, 2022). "LCN-2 is known to regulate inflammatory pathways and cytokine secretion and it plays a role in chronic inflammatory diseases, such as obesity, TDM2, or NASH." (PMID 35206286, 2022). "LCN2 seems to be a key factor linking energy intake and energy expenditure with obesity, partly explaining the excellent weight reduction in patients with higher LCN2 at baseline." (PMID 35138515, 2022). "The levels of lipocalin-2 in tissues increases with metabolic disorders such as obesity and type 2 diabetes, indicating a link between lipocalin-2 and insulin sensitivity and glucose homeostasis." (PMID 36579566, 2022). "LCN2, which is known to increase with obesity, is positively correlated with inflammation and insulin resistance." (PMID 35740306, 2022). "In particular, proinflammatory LCN2 is regulated by a transcription factor NF-κBp65, so it has been suggested that LCN2 levels can potentially be a biomarker for obesity-induced metabolic disorders." (PMID 36501079, 2022). "The LCN2-silenced mice exhibit worsened metabolic dysfunction in diet and genetically induced models of obesity, while increasing LCN2 circulating levels was suggested to promote adaptive pancreatic β-cell proliferation." (PMID 35406450, 2022). "Upregulated expression of LCN-2 is also observed in mice with obesity and is responsible for neurological degeneration." (PMID 35265399, 2022). "Initial investigations have shown that anti-diabetic drugs can counteract obesity-upregulated Lcn2 expression and circulating abundance in rats, T2D mice, and humans with T2D." (PMID 33528828, 2021). "LCN2 levels, however, are correlated with obesity and hyperglycaemia, both of which have been shown to induce and promote a chronic low-grade inflammatory state." (PMID 33603000, 2021). "Since restricted feeding and caloric restriction are effective in improving metabolic stress during disease, it is plausible that LCN2 upregulation during diet-induced obesity is an adaptive response that serves to reduce appetite and improve glucose handling." (PMID 33824339, 2021). "It is suggested that LCN2 is a possible mediator that joins obesity with chronic low-grade inflammation." (PMID 34212049, 2021).
Obesity (continued). "Elevated LCN2 levels contribute to the development of obesity-related medical complications and other pathologies, including CMD and CKD." (PMID 34938273, 2021). "Lcn2, a protein previously thought to be secreted exclusively by adipose tissue and related to obesity, has recently been found to be expressed in osteoblasts." (PMID 34016950, 2021). "In the current study, we examined LCN2 expression and found that it was elevated in gastric mucosa in obesity individuals." (PMID 33637683, 2021). "LCN2 expression is influenced by several factors including obesity, salt intake, aging, infection, and inflammatory status." (PMID 34804057, 2021). "Lipocalin 2 (Lcn2) has previously been identified as an adipocytokine and characterized as an important regulator of diet-induced obesity and inflammation." (PMID 34572499, 2021). "In particular, LCN2-related iron uptake, storage, and export appear to play a critical role in obesity-related sarcopenia." (PMID 34064680, 2021). "Altered LCN2 expression occurs under diverse pathological conditions, including kidney disease, obesity, and acute and chronic inflammatory liver disease." (PMID 34884961, 2021). "Collectively, these findings demonstrate that LCN2 functions as a potent proinflammatory factor in skeletal muscle in response to obesity-related sarcopenia and is thus a therapeutic candidate target for sarcopenia treatment." (PMID 34064680, 2021). "Adipose-derived LCN2 is highly upregulated in humans and animal models of obesity, contributing to the regulation of local, regional and systemic inflammation, immunity, and metabolism." (PMID 34938273, 2021). "Lipocalin 2 (Lcn2) has been shown to play an important role in metabolic inflammation in obesity and metabolic diseases." (PMID 34572499, 2021). "LCN2 has been proposed as an inflammatory marker for obesity, hyperglycaemia and insulin resistance, and has also been found to drive left ventricular pathological cardiac hypertrophy." (PMID 33603000, 2021). "Several studies have reported that LCN2 protein expression is upregulated in human diseases such as obesity, type 2 diabetes, and a wide range of cancers." (PMID 34903175, 2021). "Recent studies have also reported that the levels of LCN2 in blood serum, adipose tissue, and liver are increased in models of obesity." (PMID 33945675, 2021). "The inflammatory component of obesity leading to excessive production of Hep (and lipocalin 2) is considered one of the potential mechanisms of hypoferremia in obesity." (PMID 33918997, 2021). "Recent evidence suggests a beneficial effect of chronically increased LCN2 levels in patients with obesity or type 2 diabetes, as it assists in counteracting obesity-induced glucose intolerance by reducing appetite and driving beta-cell proliferation." (PMID 33905460, 2021). "Considering LCN2 is secreted primarily from parietal cells, we next further assessed the impact of obesity on parietal cells." (PMID 33637683, 2021). "The action of LCN-2 is complex, on the one hand LCN-2 is upregulated in cases of insulin resistance such as obesity and diabetes and on other hand LCN-2 has a protective effect on NAFLD." (PMID 32982804, 2020). "Previous clinical studies have also implicated a strong correlation with ectopic diseases such as cardiovascular diseases, intestinal inflammation, neuroinflammation, and other metabolic disease such as T2DM and obesity with increased Lcn2 expression." (PMID 32622362, 2020). "On the other hand, Xiaoli Chen’s group demonstrated that molecular disruption of LCN2 in mice significantly exacerbates diet-induced obesity, dyslipidemia, fatty liver disease, and insulin resistance." (PMID 33192583, 2020). "Dysregulation of LCN2 has been tied to obesity, metabolic syndrome, and cardiovascular diseases, mainly through its ability to bind to lipids like fatty acids." (PMID 32575507, 2020).
Obesity (continued). "To assess the postprandial regulation of serum LCN2, we used data from four separate studies where healthy individuals with normal weight, overweight, obesity, and severe obesity were challenged with a meal after an overnight fast." (PMID 33231171, 2020). "Lipocalin-2 (Lcn2) is an innate immune protein elevated by several orders of magnitude in various inflammatory conditions including aging and obesity." (PMID 32883997, 2020). "Several studies relate lipocalin-2 to inflammatory and dysmetabolic conditions, including obesity, the metabolic syndrome and CVD39–41." (PMID 33199796, 2020). "Previous reports suggest elevated levels of Lcn2 in obesity as a protective mechanism against inflammation and insulin resistance." (PMID 32883997, 2020). "The conflicting reports on the effects of Lcn2 on obesity warrant additional studies to investigate the mechanism behind the pro/anti-obesity effect of Lcn2." (PMID 32883997, 2020). "In this study, we have investigated for the first time the potential anti-obesity effects of rec-Lcn2 mediated through the browning of WAT." (PMID 32883997, 2020). "As obesity progresses, proinflammatory adipokines, including leptin, TNF, resistin, IL-6, RBP4, lipocalin-2, and ANGPTL-2, are preferentially synthesized and cause chronic inflammation." (PMID 33133214, 2020). "Lipocalin-2 (LCN2) is upregulated in pathological conditions such as obesity,inflammation, hypertension, and cancer." (PMID 32696819, 2020). "Despite LCN2 expression is altered in obesity, its role in the pathogenesis of this disease is not entirely clear." (PMID 33192583, 2020). "(M–O) Study 4: (M) Fold change in serum LCN2 levels in female and male individuals with obesity, before (pre) and after (post) gastric bypass (n = 12)." (PMID 33231171, 2020). "(N–O) Spearman correlation between serum LCN2 levels and hunger in individuals with severe obesity (N) before and (O) after bariatric surgery." (PMID 33231171, 2020). "In this report, using Lcn2KO and WT mice as well as in vitro studies with recombinant Lcn2 (rec-Lcn2), we have investigated the anti-obesity functions of Lcn2." (PMID 32883997, 2020). "Lipocalin-2 (LCN2) is a novel adipokine with potential roles in obesity, insulin resistance, and inflammation." (PMID 32605546, 2020). "TNF is upregulated in the presence of obesity and impacts the expression of other multiple inflammatory factors such as IL-6 and LCN2 that promote, exacerbate, and sustain chronic systemic inflammation and insulin impairment." (PMID 31892368, 2019). "Conversely, some studies showed that depletion of LCN2 in mice increased diet-induced obesity, insulin resistance, and increased expression of proinflammatory mediators, because of impaired thermogenesis." (PMID 31208019, 2019). "Our findings strongly suggest that solTNF and LCN2 interactions are a potential point of intervention for targeting inflammatory tissue-specific responses in obesity." (PMID 31892368, 2019). "When fed a HFD for 20 weeks to induce obesity, Lcn2+/+ and Lcn2−/− mice showed equivalent body weight gain." (PMID 31488870, 2019). "We conclude that LCN2 is dispensable for both high fat diet-induced obesity and its therapeutic reduction by celastrol." (PMID 31488870, 2019). "Recent evidence points to an important role of LCN2 in the pathophysiology of sterile inflammatory conditions like obesity and diabetes." (PMID 30761088, 2019). "Lipocalin-2 is an inflammatory marker closely related to obesity, insulin resistance, and obesity-related hypertension." (PMID 29731737, 2018). "In the general population levels of Lipocalin-2, have been reported to be increased in conditions such as obesity, metabolic syndrome and cardiovascular disease." (PMID 29304747, 2018). "As previously reported, pregravid obesity resulted in increased plasma levels of metabolic hormones such as insulin, leptin, and lipocalin-2, indicative of insulin resistance, mild gestational hyperglycemia, and metabolic syndrome." (PMID 30131724, 2018).
Obesity (continued). "Leptin and lipocalin-2, which are mainly produced in adipose tissues, are up-regulated in obesity and lead to the development of insulin resistance." (PMID 29783731, 2018). "In the present study, firstly we show that Lcn2 KO female mice were resistant against diet-induced obesity compared to WT mice." (PMID 29138470, 2017). "There is a hot and unsolved controversy as to a role of LCN2 in high fat diet (HFD)-induced obesity and insulin resistance." (PMID 29138470, 2017). "Neutrophil gelatinase-associated lipocalin (NGAL, lipocalin 2 or LCN2) is an iron carrier protein whose circulating level is increased by kidney injury, bacterial infection and obesity, but its metabolic consequence remains elusive." (PMID 29138470, 2017). "LCN2 has a tissue-specific role in the biosynthesis of estradiol, which links LCN2 to obesity and metabolic complications." (PMID 29234288, 2017). "Our data indicate a link between low circulating levels of TRAIL and markers of obesity-induced diseases (resistin and lipocalin-2/ngal), highlighting a new potential axis of TRAIL functions." (PMID 29056829, 2017). "Thirdly, transgenic overexpression of Lcn2 exhibited multiple metabolic effects including enhancement of diet-induced obesity, reduction of body temperature during cold exposure and suppression of cold-induced 18F-FDG uptake." (PMID 29138470, 2017). "Some studies found significant correlation between LCN2 and atherosclerosis in patients with diabetes mellitus, obesity and the metabolic syndrome." (PMID 28709459, 2017). "Clinical and experimental studies indicate an important role of lipocalin-2, FABP4, and leptin as inflammatory adipokines associated with obesity and related complications." (PMID 28757686, 2017). "Overall, these results, together with the catabolic properties of LCN2 in other joint tissues, suggest that LCN2 is an active catabolic agent in OA joints that serves as a link among obesity, ageing and OA joint alterations." (PMID 27385438, 2016). "In this work, we present evidence indicating that the expression of the obesity-related adipokine LCN2 is inhibited throughout osteoblast differentiation and is induced in osteoblasts and chondrocytes exposed to OA-related inflammatory stimuli." (PMID 27385438, 2016). "There are numerous studies available that correlated LCN2 with obesity, insulin resistance and diabetes rendering LCN2 as a possible biomarker for assessment of FLD." (PMID 27729871, 2016). "There is evidence that obesity is characterized by increased circulating levels and increased adipocyte expression of lipocalin-2." (PMID 26561830, 2015). "We and others have previously reported that Lcn2 is abundantly expressed in adipose tissue and shows upregualtion in obesity." (PMID 24818605, 2014). "Given the key role of Lcn2 in energy metabolism and obesity, it is of great importance to understand what factors regulate Lcn2 expression and secretion in adipocytes." (PMID 24818605, 2014). "Further studies are needed on the detailed mechanism for the regulation of Lcn2 expression in adipocytes, which will help understand better the role of Lcn2 in diet-induced obesity and adipose tissue inflammation." (PMID 24818605, 2014). "To understand better the role of Lcn2 in obesity and adipose tissue inflammation, we examined the regulation of Lcn2 expression and secretion in adipocytes by nutrients." (PMID 24818605, 2014). "LCN2 expression is altered in several pathologic conditions, such as adipose tissue hypoxia and obesity." (PMID 24741591, 2014). "Studies with Lcn2 knockout mice have demonstrated that Lcn2 plays a significant role in obesity and insulin resistance, brown adipose tissue activation and thermogenesis." (PMID 24818605, 2014). "Nonetheless, they suggest serum LCN2 as a useful biomarker for evaluating the outcomes in various clinical settings of obesity-related metabolic and cardiovascular disease." (PMID 24741591, 2014).